POMC (proopiomelanocortin)
Diseases named in the same sentence as POMC in open-access papers (continued):
Sharing a sentence is not in itself a finding about the gene and the disease.
Obesity (continued). "Obesity-associated PHIP variants repressed POMC transcription." (PMID 32492392, 2020). "One of them presented mutations in exon 3, with consequent deficiency of ACTH and α-MSH, and the other one had a mutation in exon 2, which prevented the translation of POMC; both patients showed adrenal insufficiency, red hair pigmentation, and early-onset obesity." (PMID 33261141, 2020). "Taken together with our findings, developmental ciliary defects disrupt the normal maturation and/or wiring of POMC neurons and causes adulthood obesity although the changes in POMC neuronal circuits may be diverse depending on the cause of the ciliary defect." (PMID 33188191, 2020). "We consider that this finding plus the associated molecular work identifying a mechanism by which disruption of PHIP can cause obesity (by disrupting transcription of POMC) establishes that some patients may present with obesity alone." (PMID 32492392, 2020). "A previous study carried out in patients with rare defects in the gene encoding POMC, showing obesity as well as hyperphagia, hypopigmentation, and early-onset hypocortisolism, showed that treatment with setmelanotide induced a decrease in appetite and significant weight loss." (PMID 33261141, 2020). "However, genes associated with obesity have been also described to be associated with HD, such as POMC, NPY, CART, and BDNF." (PMID 32982666, 2020). "However, note that the obesity phenotype induced by early postnatal disruption of POMC ciliogenesis was less remarkable than that caused by POMC-specific disruption of ciliogenesis from the embryonic period." (PMID 33188191, 2020). "The KWLPS cohort was used in conjunction with other datasets to identify a novel obesity-related (-predictive) metastable epiallele at the gene encoding pro-opiomelanocortin (POMC), which is similarly affected by maternal one-carbon donor concentration at conception." (PMID 31451874, 2019). "Moreover, chronic HFD feeding leads to POMC neuronal loss, which would lead to further progression of obesity." (PMID 31316470, 2019). "Because obesity is associated with complex changes in the neurophysiology of the POMC and AgRP/NPY neurons, the result of ARC neuromodulation by DBS on the PVN in obese patients is tricky and an optogenetic manipulation may be a preferred approach." (PMID 31057350, 2019). "In agreement with our results, it has been recently reported that treatments like proanthocyanidins, which reduce obesity-induced hypothalamic inflammation and leptin resistance, are associated with decreased caloric intake and increased gene expression of POMC in the hypothalamus." (PMID 30642033, 2019). "Therefore, the mild obesity and lower metabolic rate of Ubi-LepRNull mice are likely associated with defects in POMC or Prlh neurons." (PMID 30694175, 2019). "Interestingly, candidate genes implicated in monogenic obesity (e.g., POMC) have also been found to be influenced by DNA methylation changes contributing to common obesity." (PMID 31555578, 2019). "In addition, here we found that POMC deficiency leads to insulin resistance and glucose intolerance before the onset of obesity in ad libitum-fed female mice characterized by normal food intake, body weight and inguinal, retroperitoneal and liver fat stors." (PMID 30283405, 2018). "Therefore, TCPTP-deficiency in POMC neurons in obesity improves glucose metabolism through the repression of HGP." (PMID 30230471, 2018). "In addition, isolated obesity has been reported in carriers of POMC mutations or in association with heterozygous point mutations in POMC (especially p.Arg236Gly)." (PMID 28739551, 2018). "High fat diets have also been shown to reduce synapses on POMC neurons, and suppression of neurogenesis is reported to occur in the arcuate nuclei of mice with diet or leptin deficiency-induced obesity." (PMID 29867590, 2018). "The disruptions of POMC or MC4R in humans have been linked to early onset obesity." (PMID 29598821, 2018).
Obesity (continued). "Furthermore, diet-induced obesity is also associated with an accumulation of POMC in the ER of POMC neurons." (PMID 29457782, 2018). "Moreover, selective Mfn2 ablation in pro‐opiomelanocortin (POMC) neurons in the hypothalamus resulted in loss of ER–mitochondria contact sites, ER stress‐induced leptin resistance, reduced energy expenditure, and obesity." (PMID 29068134, 2018). "Thus, this study not only identifies ERAD as an important mechanism regulating POMC maturation within the ER, but also provides insights into the pathogenesis of monogenic obesity associated with defective prohormone folding." (PMID 29457782, 2018). "Some of these mutations would be expected to alter POMC folding and turnover in the ER; for example, an autosomal dominant POMC cysteine-to-phenylalanine mutation at position 28 (POMC-C28F) has been identified in humans with early onset obesity." (PMID 29457782, 2018). "Highlighting the significance of this gap in knowledge, a single POMC cysteine-to-phenylalanine mutation at position 28 (POMC-C28F) is defective for ER processing and causes early onset obesity in a dominant-negative manner in humans through an unclear mechanism." (PMID 29457782, 2018). "Proopiomelanocortin (POMC) deficiency is a rare monogenic disorder with early-onset obesity." (PMID 28739551, 2018). "Overconsumption of calories disrupts the pattern by causing persistently elevated TNFα, which over time causes functional impairment of hypothalamic POMC neurons, thereby generating an additional pathogenic drive towards impaired energy homeostasis and obesity." (PMID 28489068, 2017). "ADCY3/POMC has been implicated in obesity among children and adults." (PMID 28595647, 2017). "The pro-opiomelanocortin (POMC) neuronal-specific Mfn2 ablation in mice caused hyperphagia, reduced energy expenditure, endoplasmic reticulum stress-induced leptin resistance and obesity, indicating that Mfn2 plays a vital role in maintaining systemic energy balance." (PMID 29257072, 2017). "Indeed, targeted deletion of insulin receptors from POMC cells partially restored their projections to the paraventricular nucleus while also reversing the associated obesity phenotype." (PMID 25671565, 2015). "Recently, it has been shown that conditional deletion of the RNAse III ribonuclease Dicer (involved in miRNAs maturation) from POMC-expressing cells results in obesity and diabetes which is associated with a neurodegenerescence of POMC neurons in the hypothalamus." (PMID 25999818, 2015). "In the current study we tested whether conditional Sirt1 overexpression in mouse POMC or AgRP neurons prevents age-associated weight gain and diet-induced obesity." (PMID 24374551, 2014). "Protective effects of leptin during the suckling period against later obesity may be associated with changes in promoter methylation of the hypothalamic POMC gene." (PMID 24892374, 2014). "In this study, we generated conditional Sirt1 KI mouse models and asked whether conditional Sirt1 overexpression in mouse POMC or AgRP neurons prevents age-associated weight gain and diet-induced obesity." (PMID 24374551, 2014). "Lastly, in a study using 3 independent samples (N = 21, 107, and 154) of white blood cell collected in childhood or adolescence, DNA hypermethylation in intron 2 and 3 of POMC, a gene known to be related to greater BMI and obesity risk, was found to be associated with obesity." (PMID 24664798, 2014). "Using a selective ARC-deficient POMC mouse line, here we report that former obesity medications augmenting endogenous 5-hydroxytryptamine (5-HT) activity d-fenfluramine and sibutramine require ARC POMC neurons to elicit therapeutic appetite-suppressive effects." (PMID 25051442, 2014). "However, refeeding-associated weight gain and hyperphagia are dysregulated in mice with diet-induced obesity or mice carrying mutations that selectively ablate POMC neurons or that decrease levels of hypothalamic neuropeptides." (PMID 23341784, 2013).
Obesity (continued). "Furthermore, deficient ObR signaling in POMC neurons of the Arc itself leads to the development of mild obesity." (PMID 23554574, 2013). "Furthermore, GWAS studies in obesity based on more than 200,000 individuals have confirmed that genes in this pathway such as POMC and MC4R are associated with obesity." (PMID 23796690, 2013). "Based on these data, we propose a model where over-reactivity of the leptin-LepRb signaling system in hypothalamic neurons, including POMC neurons, may play a role in causing leptin resistance and obesity in high-fat fed mice." (PMID 22276206, 2012). "In conclusion, this study provides evidence that both common and rare variants in POMC could increase the risk for SD and/or obesity." (PMID 23028917, 2012). "Consistent with this “SOCS3-threshold” hypothesis, it was recently demonstrated that genetically-driven over-expression of SOCS3 in POMC neurons is sufficient to cause obesity even in chow-fed mice." (PMID 22276206, 2012). "The data support a role for POMC in the mechanisms underlying olanzapine-induced obesity." (PMID 22438946, 2012). "In addition, genetic POMC deficiency leads to obesity in humans and mice, and MC4-R deficiency leads to morbid obesity associated with enhanced adiposity and chronic hyperphagia." (PMID 22438946, 2012). "The management of obesity in POMC deficiency remains a challenge." (PMID 21860632, 2011). "Other genes such as MC4R, leptin and leptin receptor, Ghrelin (GHRL), peroxisome proliferator-activated receptor gamma (PPARG), oxytocin receptor (OXTR), prohormone convertase-1 and proopiomelanocortin have been implicated in human obesity and will be discussed elsewhere in this journal issue." (PMID 22043167, 2011). "Mutations in POMC in humans have been associated with obesity." (PMID 21205304, 2011). "Mendelian human POMC disorders are very rare, but there is linkage between POMC and other obesity related traits, suggesting that it may form part of a common genetic obesity predisposition." (PMID 17764572, 2007). "Also, while variants of uncertain significance in KIDINS220 and POMC were identified, their clinical contribution remains uncertain; ongoing monitoring is warranted given reported associations of POMC variants with obesity and of KIDINS220 variants with neurodevelopmental features." (PMID 41333852, 2025). "Based on these studies, it was hypothesized that the early microglial response to HFD consumption may be protective, whereas the sustained microglial reactivity observed in rodents with obesity may have detrimental effects, including the loss of POMC neurons in the ARC." (PMID 39937024, 2025). "In addition, setmelanotide is pioneering a personalized medicine approach to obesity, specifically targeting very rare genetic disorders such as pro-opiomelanocortin (POMC) deficiency, proprotein convertase subtilisin/kexin type 1 (PCSK1) deficiency, and leptin receptor deficiency." (PMID 40016558, 2025). "However, the impact of heterozygous POMC variants on obesity is still unclear." (PMID 40822950, 2025). "For example, setmelanotide, a melanocortin-4 receptor agonist, has shown efficacy in patients with impaired leptin-melanocortin signaling—a defect that may occur in patients with non-syndromic obesity (e.g., POMC deficiency) as well as in those with additional features (e.g., Bardet-Biedl syndrome)." (PMID 40523925, 2025). "In hypothalamic neurons expressing POMC, abnormalities in POMC processing have a critical impact on the regulation of appetite, energy homeostasis, and body composition, and mice and humans carrying deleterious mutations in the POMC gene display severe obesity and hyperphagia." (PMID 39765543, 2024). "On the other hand, specific deletion of ERα in POMC neurons of the arcuate nucleus causes hyperphagia and obesity in female mice and more recent studies suggest that specific subpopulations of POMC neurons may be integral to determining sex differences in energy balance." (PMID 36117117, 2023).
Obesity (continued). "Likewise, the deletion of autophagy-related ATG5 or ATG7 in hypothalamic POMC neurons is found to trigger abnormal glycolipid metabolism and severe obesity in the ATG5-or ATG7-deficient mice, suggesting the involvement of ER-phagy in the degradation of misfolded POMC." (PMID 37152279, 2023). "Notably, the dynamic regulation of mitochondrial shape in POMC neurons has been previously linked to the ability of POMC neurons to sense leptin, while obesity is associated with a shift toward mitochondrial fragmentation within POMC neurons and a reversible decrease incellular leptin sensitivity." (PMID 38016943, 2023). "In addition, POMC neurons might play a role in eating disorders since POMC deficiency results in obesity." (PMID 35011927, 2021). "Therefore, a HFD and obesity may cause sympathetic overactivity in a sex-specific manner through its modifications of POMC neurons, NPY neurons, and PVN glutamatergic neurotransmission." (PMID 32160920, 2020). "We have shown that the sex-specific effect of POMC peptides is associated with altered gut morphology and gut microbiota, which could be either a consequence or a cause of the Pomctm1/tm1 obesity, or both, given that there is bidirectional communication between the gut microbiome and brain." (PMID 33144604, 2020). "Importantly, previous studies indicate autophagy malfunction in hypothalamic POMC neurons contributes to obesity-associated metabolic dysfunctions, including increased plasma insulin levels, hyperglycemia, glucose intolerance, impaired lipolysis, and leptin resistance." (PMID 30972025, 2019). "Furthermore, our colocalization results indicate that the most likely scenario at this locus suggests that DNA methylation may play a role in this effect (PPA = 0.79), supporting previous findings that hypermethylation of POMC influences obesity risk." (PMID 30704512, 2019). "Gpr17 deficiency in POMC neurons protects metabolic homeostasis in a sex-dependent manner during dietary and aging challenges, suggesting that Gpr17 could be an effective anti-obesity target in specific populations with poor metabolic control." (PMID 31611548, 2019). "Our results indicate that TCPTP status may define POMC neural responses to insulin so that feeding-associated diurnal fluctuations in TCPTP or elevated TCPTP levels in obesity might dictate whether POMC neurons are activated by insulin or are otherwise inhibited or remain unresponsive." (PMID 30230471, 2018). "Routine genetic analysis in patients suspected of POMC deficiency is recommended not only to guide lonγ-term prognosis and tailor the personalized management of these patients per se, but also to enable discovery of breakthrough treatments for important public health problems such as obesity." (PMID 28739551, 2018). "Therefore, the abnormal expression of nutritional disease-associated gene POMC may definitely contribute to obesity." (PMID 29258237, 2017). "Furthermore, POMC-specific deletion of SHP2 results in mild obesity and increased susceptibility to DIO, while female mice expressing a constitutively active form of SHP2 in the brain are resistant to DIO, supporting the role for SHP2 in the control of energy homeostasis." (PMID 28270795, 2017). "Furthermore, genetic mutations in the POMC gene have been shown to cause obesity in patients." (PMID 25954145, 2015). "Recent studies suggest that impaired α-MSH signaling may also play a role in the pathogenesis of obesity: in rodents, obesogenic diets cause endoplasmic reticular (ER) stress in hypothalamic neurons, resulting in impaired POMC post-translational processing and reduced postprandial α-MSH release." (PMID 26237477, 2014). "In addition, rare POMC exonic variants may confer risk for SD and overweight or obesity through a shared mechanism." (PMID 23028917, 2012). "Thus, functional alterations in melanocortin peptides due to variation in POMC may predispose to SD and obesity, as well as other traits." (PMID 23028917, 2012).
Obesity (continued). "Thus, these rare POMC exonic variants may influence the vulnerability to SD and overweight or obesity via a common biological pathway." (PMID 23028917, 2012). "Chemogenetic activation of NTSGLP−1 significantly suppressed appetite, mitigated obesity, and modulated hypothalamic pro-opiomelanocortin (POMC) and neuropeptide Y (NPY)." (PMID 41508004, 2026). "Mutations associated with monogenic obesity follow autosomal recessive (LEP, LEPR, POMC, and PCSK1) or autosomal dominant (MC4R, SH2B1, SIM1, GNAS) modes of inheritance." (PMID 41751424, 2026). "It is important to understand the regulation of POMC and its link to obesity from a biochemical perspective to clearly describe its function." (PMID 40001512, 2025). "In a Turkish study involving 105 children with early-onset obesity and analysis of 41 genes, approximately 10.5% of the variants were found in the SIM1, POMC, PCSK1, MC4R, and LEPR genes." (PMID 40149731, 2025). "Previous study had shown that PRCP, through its involvement in the pro-opiomelanocortin (POMC) system, makes it a highly promising target in the treatment of obesity and related diseases." (PMID 41221287, 2025). "When compared to the increasingly common proopiomelanocortin (POMC) and leptin receptor (LEPR) gene mutations, melanocortin-4 receptor (MC4R) gene polymorphisms are seen to be linked to BED and obesity." (PMID 40077044, 2025). "Genetic ablation of hypoxia-inducible factor 2α (HIF2α) in POMC neurons resulted in progressive, age-dependent-obesity and body weight elevation, concomitant with the development of mild glucose intolerance and insulin resistance." (PMID 41037185, 2025). "Monogenic obesity is caused by mutations predominantly in the leptin-melanocortin system, such as LEP, LEPR, POMC, and MC4R genes." (PMID 40636093, 2025). "The disrupted expression of Ngn3 in Nkx2.1 expressing cells leads to few POMC neurons throughout life, ultimately leading to hyperphagia and early onset of obesity." (PMID 40474775, 2025). "Obesity results in a relative insensitivity to leptin signaling, and leptin insensitivity in POMC and AgRP neurons leads to obesity and diabetes in patients and animal models." (PMID 40501942, 2025). "Leptin stimulates the POMC neuron, causing release of α-MSH, which acts on MC4R, increasing satiety and reducing obesity." (PMID 41002740, 2025). "The outcome of the present study is likely to stimulate the development of strategies aimed at enhancing G12/13 signaling in POMC neurons for the treatment of obesity, type 2 diabetes, and related metabolic disorders." (PMID 40644553, 2025). "Compared to our results, a previous in vivo experiment indicated that AuNPs inhibited overeating and obesity induced by the antipsychotic olanzapine by increasing POMC cell protein expression, suggesting an effect similar to our early effect results." (PMID 40863870, 2025). "Maternal caloric restriction during pregnancy blunts the leptin neonatal surge, which impairs axon development from ARC POMC and AGRP/NPY neurons and leads to adulthood outcomes linked to vulnerability to obesity." (PMID 40474775, 2025). "Fam172a modulates POMC neuronal activity through H4K12-lactylation-dependent chromatin remodeling at neuropeptide gene loci (AgRP and POMC), with hypothalamic H4K12la levels correlating inversely with bodyweight in diet-induced obesity models." (PMID 40331975, 2025). "Overall, research on POMC neurons and their related signaling pathways provides new insights into the mechanisms of obesity regulation." (PMID 40452923, 2025). "Abnormal DNA methylations of key metabolic-related genes, such as Leptin, adiponectin, PGC1α, IGF-2, appetite-related genes-(POMC, NPY), are frequently implicated in the development of obesity and insulin resistance." (PMID 40702315, 2025). "Recent studies have identified new genetic regulatory mechanisms and potential biomarker regions for the POMC gene and MC4R secondary messenger pathway associated with obesity." (PMID 40001512, 2025).